VIM (vimentin)
Diseases named in the same sentence as VIM in open-access papers (continued):
Sharing a sentence is not in itself a finding about the gene and the disease.
tumor (continued). "Molecular analysis of the tumor tissues showed that USP22 knockdown reduced the levels of cyclin D2, Akt phosphorylation, vimentin, and Bcl-2, whereas upregulated the expressions of E-cadherin, Bax, and cleaved (cl)-caspase-3, which confirmed in vitro findings." (PMID 27145278, 2016). "In tongue squamous cell carcinoma, the membranous localization of E-cadherin was reduced in tumor buds as compared to the main tumor mass, while vimentin levels were positive in tumor buds but not in the main tumor mass." (PMID 27136592, 2016). "Histopathological analyses revealed the tumours to be spindle cell masses consistent with fibrosarcomas and sections stained positive for the mesenchymal marker, vimentin (data not shown)." (PMID 26900951, 2016). "The intermediate filament cytoskeleton of the cultivated cells, irrespective of their morphology, was composed of vimentin as expected for mesenchymal cells and as also seen in the corresponding histological tumor sections." (PMID 29056719, 2016). "IHC showed that these tumor cells were diffusely positive for vimentin, focally positive for cytokeratin and EMA, and negative for S-100, bcl-2, and c-kit." (PMID 27068820, 2016). "Tumors with a highly epithelial phenotype expressed low levels of vimentin, which was restricted to stromal cells (PtW, OVCAR5) and high levels of CD44v8-10 expression, which was specific to the cell surface of the cancer cells of the tumor (insert)." (PMID 27253518, 2016). "Tumour-derived and normal cell isolates were characterised as positive for osteocalcin, osteonectin, type 1 collagen, alkaline phosphatase and vimentin and negative for EpCam." (PMID 26974205, 2016). "In our experiments vimentin upregulation was detected in the insoluble fraction of cells from primary tumor as well as in metastatic cell line lacking adhesion rings, which suggests that vimentin recycling or function was disrupted." (PMID 27075696, 2016). "Immunohistochemical examination showed that tumor cells were positive for vimentin and p63 and negative for NSE and Cd56 markers." (PMID 27765044, 2016). "In all cases a significant reduction in tumor methylated vimentin was seen between treated and non-treated samples, P < 0.01." (PMID 27542211, 2016). "To determine whether the tumor cells were expressing markers of differentiation, we analyzed glial fibrillary acidic protein (GFAP) and vimentin at 2, 5 and 10 dpt." (PMID 26659251, 2016). "At other sites within the same tumor, the epithelium and stroma can exhibit positive or negative expression of both vimentin (B) and E-cadherin (C)." (PMID 27590006, 2016). "Vimentin expression was correlated with depth of tumor invasion, but not with the other clinicopathological characteristics (P > 0.05)." (PMID 26916665, 2016). "Immunohistochemically, pan-keratin, thyroglobulin, and S100 were negative in tumor cells, whereas vimentin, desmin, and smooth muscle actin were found to be positive." (PMID 27080750, 2016). "Immunohistochemical analyses demonstrated markedly increased vimentin levels in tumor tissues compared to their paired noncancerous liver tissues." (PMID 26824421, 2016). "But in most of the cases, negative for vimentin expression was found in the ductal component of the tumor." (PMID 26906973, 2016). "The tumor showed strong immunoreactivity for vimentin and S-100 and negative immunoreactivity for CD-68." (PMID 27525129, 2016). "Furthermore, this close correlation was confirmed in tumor tissues from a large cohort of HCC patients, and the combination of OPN and vimentin had a better prognostic performance than OPN or vimentin alone." (PMID 26824421, 2016). "Tumor size, cell type (clear/granular), Fuhrman’s grade, Staging, as well as immunostaining with Snail, ZEB1, Twist, Vimentin, E-cadherin, β-catenin, PTEN, p-Akt, p110α, and SETD2, were analyzed for intratumor heterogeneity using a classification and regression tree algorithm." (PMID 26951092, 2016).
tumor (continued). "Tumor proliferation- and invasion-related biomarkers, including Ki67, MMP9, E-cadherin, N-cadherin, β-catenin, and Vimentin, were examined in 100 HCC primary tissue samples to determine whether NTS+NTR1+ promotes tumor invasion." (PMID 27611941, 2016). "Tumor cells are reactive with GFAP and vimentin, either diffusely or focally." (PMID 27568373, 2016). "In particular, we observed that SAHA treatment could significantly reduce the percentages of tumor cells with positive staining of THBS1, Nestin, N-cadherin, SNAIL/SLUG, Vimentin and b-catenin." (PMID 27634890, 2016). "Positive expression of vimentin was observed in 79.5% (70/88) of tumor tissues, but only in 42.9% (18/42) of noncancerous tissues; this difference was statistically significant (P < 0.001)." (PMID 26916665, 2016). "Therefore, vimentin expression is one of the primary indicators of the development of EMT in carcinomas, which suggests a tumor with an aggressive phenotype with invasive and/or metastatic potential." (PMID 26095281, 2015). "Moreover, implantation of the PEM inhibited tumor-stromal interaction-related expression of proteins such as CD44, SPARC, matrix metalloproteinase-2, and vimentin." (PMID 25983747, 2015). "Immunohistochemically, the tumor showed strong and diffuse staining for CD34, bcl-2, and vimentin; other markers, such as pan-cytokeratins, EMA, desmin, alpha-smooth muscle actin, and S-100 protein, were negative and had a high mitotic index (seven mitoses per 10 high-power fields (HPF))." (PMID 25649645, 2015). "Immunohistochemical staining of the tumour had shown positive staining for vimentin and weakly positive staining for actin as well as negative staining for desmin." (PMID 26640482, 2015). "Immunohistochemically, the rhabdoid cells were positive for vimentin, whereas the tumor cell nuclei were mostly negative for BAP1." (PMID 25588411, 2015). "Immunohistochemically, the tumor cells were positive for cytokeratin (CK) and vimentin, but negative for CK20, CK7, desmin and smooth muscle actin." (PMID 25788994, 2015). "Importantly, cancer cells in human primary tumor tissues that were CCR1, CCR3 or CCR5-positive expressed high levels of vimentin." (PMID 25788271, 2015). "Keratin-31, vimentin, prohibitin, etc., were up-regulated in tumour stroma; Rho GDP dissociation inhibitor (GDI) β, superoxide dismutase, keratin-19, and annexin-A2 were down-regulated in tumour stroma." (PMID 26184160, 2015). "Dual immunofluorescence for CR-1 and vimentin, in most instances, showed the absence of vimentin in tumor cells while expression was found in the stromal contingent." (PMID 25596738, 2015). "Moreover, the nested spindle/ovoid tumor cells among the alveoli were AE1/AE3+, EMA+, CK7-, TTF-1-, PE10-, p63+, CK5/6+, CK10/13+, and vimentin-." (PMID 26205138, 2015). "Immunostaining of the low- and high passage cells (middle and bottom rows) revealed that the in vitro cultured cells maintained expression of EMA, N-cadherin, and vimentin, and also were negative for E-cadherin as was the original tumor (top row)." (PMID 26174772, 2015). "His immunohistochemistry analysis showed that the tumor cells were positive for vimentin, CD34, BCL-2 and beta-catenin, and negative for pan Cytokeratin, p63, Calretinin, SMA, desmin, S100, CD-31, CD-117, DOG1, EMA, STAT6, GRIA2 and WT-1." (PMID 25884588, 2015). "Immunohistochemically, the tumor cells were positive for vimentin and smooth muscle actin and negative for anaplastic lymphoma kinase." (PMID 25688324, 2015). "Given that Vimentin, MMP2 and Fibronectin are well-known key players of the epithelial-mesenchymal transition (EMT) process in promoting tumor metastasis; our results indicated a pro-metastasis function of RIPK4 by promoting the EMT process in the progression of CSCC." (PMID 26148476, 2015).
tumor (continued). "When no CAFs were closely situated to the LNCaP organoids, they did not express mesenchymal markers like vimentin, but formed solid round structures surrounded by an intact basal lamina, which prohibited tumor cells to escape from the organoid." (PMID 26375443, 2015). "Immunohistochemical staining demonstrated the tumor cells were strong positive for vimentin and smooth muscle actin, while negative for S-100 protein." (PMID 26303928, 2015). "In particular the presence or absence of Vimentin staining of paraffinized tumor samples can be of great importance for the differentiation between malignant and benign tumors." (PMID 25944973, 2015). "Also, DAPI staining allows for multiplexing of diverse stains, allowing for staining of additional proteins that can, e.g. discriminate the tumor (PCK) and stromal (vimentin) compartments." (PMID 25976920, 2015). "Compared with those from other groups, the expression of TGF-β1, Vimentin, ZEB-1, N-cadherin, Gli1/2, and P-Smad2/3 was significantly decreased in the tumor areas from the mice vaccinated with B16F10/GPI-IL-21 combined with the B16F10/shTGF-β1 challenge and the administration of miR200c agomir." (PMID 25895132, 2015). "In accordance, a significant reduction of E-cadherin expression and an increase of the vimentin/E-cadherin ratio were found in “R1” patients compared to “non-R”1 tumours." (PMID 26474461, 2015). "Mouse mammary EpRas tumor cells were treated with 5 ng/ml of TGF-β1 for 48 h, or with 2 ng/ml for 7 days or 14 days (long-term) to study the effect on the commonly used EMT markers E-cadherin and vimentin." (PMID 25674539, 2015). "Since E-cadherin is downregulated in tumor cells expressing N-cadherin but not vimentin or fibronectin, cadherin switching represents the best marker of EMT in PCa patients." (PMID 26041890, 2015). "Furthermore, tumor cells displayed a positive immunoreaction for melanocytic markers S100 and HMB-45 combining with positive vimentin and cytokeratin AE1/AE3." (PMID 26628037, 2015). "The tumor cells from the two maxillary LGMSs, including the recurrent lesion, were positive for vimentin and fibronectin, and negative for S-100 protein, CD34, EMA, h-caldesmon, ALK, MSA and calponin." (PMID 25624890, 2015). "Regardless of tumor-cell type, vimentin positive staining was always observed as a peripheral capsule —this type of binding pattern was never observed in spheroids derived solely from tumor cells (data not shown)." (PMID 26208323, 2015). "We observed a significant decrease in E-cadherin expression and a significant increase in vimentin in tumor cells in the cetuximab group but not in the controls (data not shown), as semi-quantified by histoscore." (PMID 26437222, 2015). "Western blot and immunohistochemistry of tumours revealed abundant mPGES-1 and vimentin expression in mPGES-1SC, contrasting with the absence of these two proteins in mPGES-1KD tumours." (PMID 26113609, 2015). "We demonstrated that N-cadherin, vimentin and fibronectin were generally not co-expressed in corresponding tumor regions." (PMID 26041890, 2015). "Tumor stroma with strong Hsp27 and α-SMA staining was also highly positive for vimentin." (PMID 25793600, 2015). "Immunohistochemical staining of the tumour revealed strong cytoplasmic positive staining for actin, desmin, and vimentin, but there was negative staining for keratin and S-100 protein." (PMID 26640482, 2015). "Immunohistochemically, the tumor cells were positive for vimentin and cluster of differentiation 34, while they were negative for keratin, PDGFRA, smooth muscle actin, desmin, S-100 protein, DOG-1 and c-kit." (PMID 25435986, 2015). "Downregulation of E-cadherin was demonstrated in all N-cadherin positive tumor cells, but not in vimentin or fibronectin positive tumor cells." (PMID 26041890, 2015).
tumor (continued). "In order to assess which component of the tumor contributed to the cancer cell lymphatic vessel invasion, the level of vimentin expression was analyzed in the MPP and non-MPP components, as well as in the cancer cells in each lymphatic vessel." (PMID 25120667, 2014). "In the present case, the tumor cells were positive for vimentin, CD68 and Ki-67, and negative for S-100, SMA, desmin, CD31, CD34, ALK and AE1/AE3." (PMID 24959221, 2014). "When we analyzed tumor tissues from PC3 xenografts obtained by co-inoculation with WI38C, we observed that MCT1 was expressed by tumor cells while MCT4 was mainly localized in vimentin/α-SMA-positive stromal cells." (PMID 24597899, 2014). "Consistent with their origin from stromal cells, these four primary malignant PTs, their non-tumor part, and their xenografts all lacked cytokeratins, but expressed vimentin except non-tumor parts of patient BC515." (PMID 24670249, 2014). "Immunohistochemical studies showed that the tumor cells expressed strong immunoreactivity for vimentin (VIM) and negative for cytokeratin (CK), suggesting a mesenchymal histogenesis." (PMID 24444015, 2014). "The tumor cells stained positively for vimentin, inhibin and α-smooth muscle actin, but not for the α-helical rod domain of desmin, which aided in confirming the diagnosis of ovarian leiomyoma." (PMID 25360170, 2014). "CKpan was expressed in cuboidal tumor cells in some cases (14/18) but not in polygonal tumor cells in any case (0/18, 0%).Vimentin was diffusely expressed in polygonal tumor cells(18/18, 100%)and in cuboidal tumor cells in some cases(6/18)." (PMID 25130377, 2014). "Our results show that in the pathological skeletal remain several well known tumor biomarkers are detected such as annexin A10, BCL-2-like protein, calgizzarin, rho GTPase-activating protein 7, HSP beta-6 protein, transferrin and vimentin compared to the control samples." (PMID 24475253, 2014). "It has been previously demonstrated using immunohistochemistry that the tumor cells usually express vimentin and smooth muscle actin, but are negative for desmin, and these results are in accordance with this proposal." (PMID 25120611, 2014). "Immunohistochemical staining of the tumour showed positive reaction to the tumour cells for Vimentin, S100 protein, and Melan A and negative reaction for muscle actin, smooth muscle actin, desmin, and HMB-45." (PMID 25374957, 2014). "The tumor cells showed immunopositivity for CD10, progesterone receptor and vimentin." (PMID 24993459, 2014). "In the reported case the tumour showed strong positive expression of NSE, Syn and vimentin." (PMID 24443792, 2014). "Microscopically, the tumor had foci of conventional adenocarcinoma (CK7-positive and CA19-9-postive) surrounded by malignant-appearing spindle cells that were positive for cytokeratins and vimentin." (PMID 24804133, 2014). "It is known that the increased expression of TGF-β, Vimentin, ZEB-1and N-cadherin could promote EMT progression of tumor cells, whereas the decreased expression of SMAD-7 and E-cadherin could inhibit the EMT progression." (PMID 24625224, 2014). "Interestingly, the levels of SRC and PPARB/D expression were highly and significantly correlated in these tumours, as were the expression levels of PPARB/D andTGFB1 and MMP19, respectively, and to a lesser extent, MMP2, VEGFA, VIM and SNAI1." (PMID 24203162, 2014). "The positive expression of vimentin protein was observed in 30% (30/100) of tumor tissues, but 0% (0/58) of noncancerous tissues (P<0.001)." (PMID 25464508, 2014).
tumor (continued). "On immunohistochemical staining, the tumor cells were positive for vimentin and CD99, but negative for alpha smooth muscle actin, desmin, and S-100 protein." (PMID 24969223, 2014). "The use of EMT markers, e.g., vimentin, facilitated the capture of EpCAM/CK double-negative tumor cell in peripheral blood." (PMID 24886394, 2014). "Accumulation of myofibroblasts in turn correlated with increased L1CAM expression in ductal and tumor cells supporting experimental data on the role of macrophages and myofibroblasts in the induction of EMT by upregulating vimentin and L1CAM in ductal and PDAC cells." (PMID 24797069, 2014). "We found that OTUB1 regulated vimentin in CRC cell lines, although vimentin expression in the tumor stromal cells of CRC tissues was not correlated with OTUB1 expression." (PMID 25431208, 2014). "Immunohistochemical studies revealed that the tumor cells was positive for VIM and MDM2, and was negative for CK, MSA, SMA, DES, S-100 and CD34." (PMID 24444015, 2014). "Increased metastatic abilities of tumor cells in N+ patients could be therefore attributed to expression of CXCR4, uPAR and VIM (and possibly SNAIL)." (PMID 24709997, 2014). "Immunohistochemically, the tumor cells, including signet-ring cells, were diffusely positive for S-100 protein, vimentin and Melan-A, but negative for HMB-45, cytokeratin (AE1/AE3 and CAM5.2), nestin, peripherin, α-internexin and GFAP." (PMID 24348822, 2014). "The CK+ and/or vimentin+ events were then subjected to CD45 negative gating to distinguish tumor cells from WBCs and/or debris." (PMID 24886394, 2014). "The tumor cells showed immunopositivity for β-catenin, CD10 and vimentin." (PMID 24993459, 2014). "Only the stroma of the human tumor and not the one in the xenografts showed positive staining for Vimentin and WT-1." (PMID 24594904, 2014). "Immunohistochemistry showed the tumour cells to be positive for synaptophysin, vimentin, and melan-A and negative for chromogranin." (PMID 24716005, 2014). "Notice that positive-vimentin (tumor) cells are not labeled for IB4, indicating that recruited microglia are exclusively originated from brain parenchyma." (PMID 25482099, 2014). "In present study, vimentin was not expressed in cancer cells but was expressed in tumor stromal cells in CRC tissues, which is in accordance with previous studies." (PMID 25431208, 2014). "Immunohistological studies revealed that the tumor yielded positive staining for p63, vimentin, CD34 and CD68, but was negative for SMA, CD38 and cytokeratin." (PMID 25120721, 2014). "Consistent with the western blot results, the expression of TGF-β, Vimentin, ZEB-1 and N-cadherin detected by immunohistochemistry assay was also remarkably decreased, whereas the expression of SMAD-7 and E-cadherin was notably increased in the tumor tissues." (PMID 24625224, 2014). "Immunohistochemically, the tumor cells were positive for S-100 protein, vimentin and BCL-2, and negative for HMB45, Melan-A, CD117, CD34 and CD99." (PMID 25364450, 2014). "Here we present data that a variable fraction among the circulating tumour cells detected by the Maintrac® approach expresses mRNA of the stem cell gene NANOG and of the adhesion molecule vimentin and is capable of forming tumour spheres, a property ascribed to tumour-initiating cells (TICs)." (PMID 23983815, 2013).